IL7R (interleukin 7 receptor)
Diseases named in the same sentence as IL7R in open-access papers (continued):
Sharing a sentence is not in itself a finding about the gene and the disease.
cancer (continued). "Overall, the CA19-9 level increased and the IL-7R level decreased as the cancer progressed." (PMID 35159120, 2022). "Furthermore, we summarize and discuss the recent advances in the use of IL-7 and IL-7Rα as cancer immunotherapy tools and highlight their potential for therapeutic applications." (PMID 36142322, 2022). "Because IL-7R represents the host response to cancer, its expression can be host specific and may decrease as the cancer grows." (PMID 35159120, 2022). "Interestingly, the expression levels of four genes (PDGFB, CCND2, CTF1, IL7R) identified in the current study were strongly associated with STAT3 activation, clinical outcome of LUAD patients and drugs sensitivity across cancer cell lines in GDSC." (PMID 34301211, 2021). "Finally, IL-7 and IL-7R play critical roles in the impaired immune systems of patients with cancer." (PMID 39086683, 2023). "Moreover, the crucial role of IL-7/IL-7R axis is especially relevant in the context of cancer." (PMID 34575268, 2021). "The pro-inflammatory cytokines bind to the IL7R and trigger the JAK/STAT pathway, promoting cancer progression." (PMID 40408005, 2025). "Immune-modulating proteins such as CXCR4, CD40, IL7R, TGFBR1, and SEMA4D are frequently targeted for cancer intervention studies." (PMID 40805206, 2025). "Within this set of genes, a subset, notably CSF2RA, CRLF2, IL1R1, IL7R, and PDGFRB, exhibited intricate connections with the JAK-STAT pathway, which is crucial for the viability of cancer cells." (PMID 38743676, 2024). "JQ1 has been proven to be a first-in-class BETi, which can downregulate the transcription of multiple genes through targeting BRD4, such as MYC, IL7R, and E2F1 in different cancer cells." (PMID 36499487, 2022). "We found that the mRNA expression of IL7R, COL22A1, ZNF185, and SRD5A2 were upregulated in cancer tissues, while PTGS2 and CLDN1 were higher in normal tissues, consistent with our previous analysis." (PMID 35813821, 2022). "In the thyroid, 16 of the SBGs were previously reported as cancer drivers, with 11 being over-expressed in females’ normal thyroid, including the oncogenes CARD11, EZH2, and IL7R." (PMID 32849808, 2020). "Here, we developed and characterized a fully human monoclonal antibody against IL-7Rα, providing clear proof-of-concept for the development of antibody-based treatments for T-ALL and other cancers relying on IL-7/IL-7R-mediated signals." (PMID 30850736, 2019). "Several lncRNAs, such as lncRNA-MIAT, lnc-IL7R and RP5-833A20.1, have been reported to regulate inflammation factors in other cancers; however, lncRNAs that have been reported to regulate inflammation in CCA is limited." (PMID 30305026, 2018). "FOSL1, BCL2, CDK6, IL7R, RUNX2 and CDC25B have been shown to be targets of JQ1 for transcriptional silencing in other types of cancers." (PMID 27764802, 2016). "Notably, CD34, IL7R, NRP1, GZMB, FGF7, and ENO2 exhibited significant expression in cancer stem cells, CD4+ memory cells, regulatory T cells, NK cells, fibroblasts, and neurons, respectively." (PMID 38846945, 2024). "Remarkably, IL7R, FLT3, C1QC, and HLA-DRB5 were all negatively correlated with cancer purity." (PMID 35300397, 2022). "In this study, IL-7R expression was lower in patients with systemic cancers than in those with PDAC, suggesting that this expression can be used to differentiate PDAC from other carcinomas." (PMID 35159120, 2022). "Interestingly, certain studies in recent years have found that IL7R may be directly related to cancer; however, the function of IL7 and the IL7R may result in dual outcomes." (PMID 37381714, 2023).
cancer (continued). "Additionally, IL7R signaling, important for the survival and proliferation of naive and memory T cells as previously discussed, was also reduced in Arms B and C as compared to Arm A. Within our data, IL7, a ligand for IL7R, was detected in Tregs and cancer cells." (PMID 39811671, 2025). "Therefore, IL-7R, which is upregulated when directly co-cultured with macrophages, may contribute to ESCC progression by promoting the development of various malignant phenotypes in cancer cells." (PMID 36672342, 2023). "Conversely, IL-7 receptor (IL7R) and LAMA2, two genes that are upregulated in a number of cancers, were targeted by REST only in the two non-tumorigenic differentiated cell types." (PMID 24922058, 2014).
inflammation (6 papers, 2009 to 2025). Aberrant reaction of the microcirculation characterized by movement of fluid and leukocytes from the blood into extravascular tissues. "We extended therefore the analysis of cellular immune abnormalities associated with CNS inflammation to the number of Il-7R molecules on the single cell level." (PMID 19657390, 2009). "Studies have shown that certain drugs can successfully treat lung inflammation by blocking the IL-7/IL-7R pathways between macrophages and epithelial cells." (PMID 40333951, 2025).
hematological cancer (5 papers, 2021 to 2026). "The IL-7/IL-7R axis has been well characterized in the context of immune development and hematologic cancers." (PMID 41360767, 2025). "Furthermore, activation of IL7Rα and γc heterodimeric complex stimulates JAK3‐STAT5 signaling pathway, driving hematological cancer development, implicating therapeutic relevance of IL7R as a therapeutic target." (PMID 34159752, 2021). "Indeed, IL-7/IL-7R-mediated signaling plays an oncogenic role in hematological tumors by may being resistant to conventional chemotherapy and targeted therapeutics." (PMID 34575268, 2021).
infectious disease (5 papers, 2010 to 2023). A disorder directly resulting from the presence and activity of a microbial, viral, or parasitic agent in humans. "Several SNPs in the IL7Rα gene have been associated with immune and infectious diseases." (PMID 35907923, 2022). "In our study there was a hypothesis supported by theory and previous reports in several infectious diseases, including HIV infected subjects and HIV/HCV coinfected patients, and showing a key role of IL7R polymorphisms in the evolution of patients." (PMID 26123260, 2015). "Notably, compared to the canonical gene, the IL7R variants 5-35874473-C-T (rs6897932), 5-35860966-T-C (rs1494558) and 5-35871088-G-A (rs1494555) alter the pathology of autoimmune and infectious diseases due to their impact on IL7R expression and alternative splicing." (PMID 38577257, 2023). "With respect to Tregs, IL-7R agonists have been reported to reduce their immunosuppressive properties, potentially enhancing the therapeutic utility of MDK-703 in oncology and infectious disease." (PMID 37874823, 2023).
hematologic malignancies (4 papers, 2011 to 2026). "In addition to hematologic malignancies, IL-7/IL-7R signaling is implicated in the progression of various solid tumors." (PMID 41596598, 2026).
adenocarcinoma (2 papers, 2022 to 2023). A common cancer characterized by the presence of malignant glandular cells. "According to TCGA and Oncomine database analysis, IL7R expression in adenocarcinoma tissues was significantly lower than that in normal lung tissues and was further verified in clinical tissue samples." (PMID 35264973, 2022).
neurologic diseases (2 papers, 2009 to 2022). "We did not observe significant differences between healthy donors or patients with neurological diseases in IL-7R (CD127+) frequency or receptor density on Treg cells." (PMID 19657390, 2009). "Only 2/59 immune cell phenotypes showed significant differences in the comparison of PBMCs from healthy individuals and patients with neurological diseases: TCRαβ+CD4+CD25−CD107a+ T-cells expressed higher numbers of IL-7R molecules as compared to PBMCs obtained from control individuals." (PMID 19657390, 2009).
genetic disorder (1 paper, 2019). "In summary, we are presenting a unique case where five unrelated patients share the same mutation in a rare genetic disorder of IL7Rα deficiency with divergent clinical course." (PMID 31379863, 2019).
neurodegenerative disease (1 paper, 2025). A disorder of the central nervous system characterized by gradual and progressive loss of neural tissue and neurologic function. "Twenty-seven of these associations are known disease loci reported in GWAS, including APOE, MME, CD2AP, CD33 and IL34 for AD, and CD40, CD58, EVI5, IL7R and STAT3 for MS, and 23 associations represent previously unreported genetic associations with neurodegenerative diseases." (PMID 40037332, 2025).
retinopathy (1 paper, 2021). "However, retinopathy is a unique model and reflects small vessel disease; thus, further studies are necessary on IL-7R and miR-424-5p in large vessel disease (CVD)." (PMID 33985567, 2021).
IL7R also shares sentences with these, for which no sentence is quoted: Crohn disease (12 papers); co-infection (8); bladder cancer (5); combined immunodeficiency (4); latent infection (4); acute hepatitis B (3); acute pancreatitis (3); bacterial infection (3); chronic obstructive pulmonary disease (3); Cirrhosis (3); gastric cancer (3); graft versus host disease (3); head and neck squamous cell carcinoma (3); Hepatitis (3); Hypertension (3); metastatic melanoma (3); pancreatic ductal adenocarcinoma (3); preeclampsia (3); primary Sjögren’s syndrome (3); T cell deficiency (3); amyotrophic lateral sclerosis (2); breast tumor (2); chronic hepatitis B (2); chronic lymphocytic leukemia (2); chronic myeloid leukemia (2); chronic pancreatitis (2); chronic periodontitis (2); cutaneous melanoma (2); DiGeorge syndrome (2); Failure to thrive (2).
A further 171 diseases each share a sentence with IL7R in 2 papers or fewer.